ZEB1 (zinc finger E-box binding homeobox 1)
Diseases named in the same sentence as ZEB1 in open-access papers (continued):
Sharing a sentence is not in itself a finding about the gene and the disease.
cancer (continued). "According to reports, miR-200s can affect ZEB1 and/or ZEB2 expression in many types of cancer, such as gastric cancer, non-small lung cancer and oral squamous cell carcinoma." (PMID 37239035, 2023). "A key way how p38 promotes EMT in cancer cells is by stabilizing and increasing the function of some of the EMT core transcription factors such as SNAIL, ZEB1, and TWIST1." (PMID 37009481, 2023). "ZEB1 (Zinc finger E-box binding homeobox 1) is a transcription factor, known for its role in the Epithelial–Mesenchymal Transition (EMT) in cancer." (PMID 36982917, 2023). "In recent years, various studies have analyzed the impact of the zinc finger E-box-binding homeobox 1 (ZEB1) and zinc finger E-box-binding homeobox 2 (ZEB2) homologous transcription factors on carcinogenesis and cancer progression." (PMID 37174083, 2023). "Meanwhile, the critical transcription factors, including TWIST1, TWIST2, ZEB1, ZEB2, SNAI1 and SNAI2, participate in the EMT process, leading to cancer cell migration and invasion." (PMID 37794509, 2023). "The authors also demonstrated that Zeb1 expression promoted post-invasive events in PDAC, that is, enhanced stemness, tumourigenicity and metastatic capacity of cancer cells." (PMID 37550301, 2023). "Together with YAP1 several EMT-TFs (ZEB1, ZEB2, TWIST2) are upregulated in cancer cells after contact with fibroblasts." (PMID 36936987, 2023). "The activation of genes such as NR4A3, MET, ZEB1, CSF1, CSF2, CSF3, which can be involved in transcriptional dysregulation in cancer or hematopoietic cell lineage signaling pathways, can also be involved in cell differentiation." (PMID 37606991, 2023). "Upstream mediators of EMT, such as ZEb1/2, TGF-β, and microRNA regulate response of cancer cells to Paclitaxel and docetaxel." (PMID 36186418, 2022). "Zeb1, a critical regulator of EMT, increased the expression of LC-3II and the resistance of TNBCs to anti-cancer drugs." (PMID 36076996, 2022). "ZEB1 promotes epithelial-mesenchymal transition (EMT), cancer cell plasticity, dissemination, and drug resistance." (PMID 35173307, 2022). "ZEB1, as a major EMT (Epithelial-Mesenchymal Transition) inducer, can promote cancer cell migration and metastasis by repressing the expression of its target gene E-cadherin." (PMID 36273188, 2022). "To identify the correlation between ZEB1 and ZEB2 expression, we analyzed this correlation in 32 cancer types using the TIMER database." (PMID 35723302, 2022). "The low expression of ZEB1 can impede EMT, reducing the sensitivity of cells to ferroptosis, which will weaken the ability to resist cancer." (PMID 35232428, 2022). "The seven-in-absentia (Siah) ubiquitin ligases have been reported to decrease the stability of the ZEB1 protein through the ubiquitin-proteasome pathway; this subsequently affects the EMT process in mammalian cancer cells." (PMID 36499447, 2022). "miR-205 also regulates EMT by targeting ZEB1 and ZEB2 and inhibits cancer cell migration and invasion in PCa." (PMID 35454801, 2022). "Among the genes corresponding to DNA methylation in the prognostic signature, we identified that ZEB1 and DUOX1 are drivers of ferroptosis and that CISD1 is a suppressor of ferroptosis, which play a crucial role in cancer development." (PMID 36555319, 2022). "The same mechanism of reciprocal inhibition occurs between the ZEB1 and miR-200 family; thus, by blocking miRNA translation, the ZEB1 and ZEB2 proteins can upregulate their expression in several cancers." (PMID 35267528, 2022). "However, whether Zeb1 regulates the aberrant metabolism of cancer glycolysis is unclear." (PMID 35246504, 2022). "We also checked expression of EMT markers, such as E-Cadherin, Krt12, Vimentin, Survivin, Slug, ZEB1 and ZEB2, in the TNBC cancer cells, and found that expression of ZEB1 was positively correlated with expression of SENP1." (PMID 35342335, 2022).
cancer (continued). "In cancer, Snail can induce endothelial-to-mesenchymal transition (EMT) in epithelial cells while Zeb1/2 and Twist maintain the invasive mesenchymal phenotype." (PMID 36291145, 2022). "lncRNA ADPGK-AS1 (human chromosome 15q24.1) overexpression promotes PDAC progression via the ceRNA mechanism involving miR-205-5p by activating ZEB1-mediated EMT, suggesting a link between cancer glycolysis control and EMT induction." (PMID 36452037, 2022). "This corroborates previous findings linking their EMT-TF targets (ZEB1, SNAI1 and SNAI2) with cancer stem cells in CRC." (PMID 35565409, 2022). "IL-1β induces ZEB1, a mediator of EMT formation, and ICAM-1 expression, which promotes adhesion and self-renewal of cancer stem cells (CSC)." (PMID 35884974, 2022). "We have also reported that, in murine mammary gland epithelial NMuMG cells, Ets1 enhances ZEB1 promoter activity during EMT induced by transforming growth factor‐β (TGF‐β), a well‐known inducer of EMT during development, fibrosis, and cancer progression." (PMID 35451213, 2022). "Silencing ZEB1 also decreases PD-L1 as an immune checkpoint ligand along with the downregulation of miR200 and consequently EMT activations in cancer cells." (PMID 36402997, 2022). "Expression of mesenchymal-like markers (ZEB1, CDH1) is correlated with AgNP sensitivity in breast, lung, and ovarian cancer cells." (PMID 35887576, 2022). "Hence, ZEB1 may be an important factor in the generation of UM cancer stem cells." (PMID 35404029, 2022). "The activity of NF-κB has been demonstrated to stimulate the induction of ZEB1 and EMT through the action of interleukin-17 (IL-17) and phosphorylation of ezrin Tyr353, respectively, in different cancers." (PMID 36402997, 2022). "One significant feature of these phenotype cancer cells was their high expression of mesenchymal markers, such as CDH2, S100A4, MMP2, WNT5A, and ZEB1." (PMID 36553542, 2022). "It has been known that the PI3K-Akt pathway facilitates the expression of EMT-related transcription factors Snail, Slug, ZEB1, and ZEB2, thereby promoting EMT and enhancing the motility of cancer cells." (PMID 36009568, 2022). "ZEB1, a well-known regulator of EMT, drives migration and metastasis, and appears to be a central switch in cancer cell determination." (PMID 35563733, 2022). "TAZ-ZEB1 cooperation in H. pylori-induced GC is demonstrated by TAZ silencing, which decreases ZEB1 expression and EMT, as well as invasion and cancer stem cell (CSC) tumoursphere formation properties acquired by GC cells after H. pylori infection." (PMID 35565411, 2022). "TGF-β acts as a potent marker for the activation of ZEB1 and Smad2, which promote EMT, tumorigenesis, and cancer recurrence." (PMID 36402997, 2022). "Future experimental studies will be required to determine the differential contribution of ZEB1 and EMT to Erlotinib resistance in human cancers." (PMID 35618721, 2022). "There are a number of factors known as EMT-inducing transcription factors (EMT-TFs), including ZEB1/2, TGF-β, Snail, Slug, and Twist, which can stimulate EMT in cancer cells and promote tumor invasion." (PMID 35765040, 2022). "We found that coexpression of cancer stem cell (CSC) and epithelial-to-mesenchymal transition (EMT) markers such as OCT4 and ZEB1 are indicative of poor outcome." (PMID 36358805, 2022). "In colorectal cancer, aggressive cancer cells where both the ERK and NF-kB pathways are activated show high ZEB1 levels through FOXK2 transcription factors activated by both signaling pathways." (PMID 36140527, 2022). "On the other hand, high mesenchymal state cells (including some therapy-resistant cancer cells) and certain EMT cells (in particular, those induced by Zeb1) are hypersensitive to ferroptosis inducers." (PMID 35883651, 2022). "ZEB1 is a crucial transcription factor in the epithelial–mesenchymal transition (EMT) process and is involved in the embryonic development and cancer proliferation." (PMID 36139015, 2022).
cancer (continued). "Conversely, the mesenchymal markers fibronectin and vimentin, the cancer stem cell marker CD44, the EMT‐TFs Zeb1 and Snail were all strongly increased." (PMID 35348275, 2022). "We have also examined the levels of the EMT-TFs such as TWIST1, SNAIL, SLUG, ZEB1, and ZEB2 because targeting these factors has been suggested as potential cancer therapeutics." (PMID 35774120, 2022). "For example, ZEB1 is a major element in the control of epithelial-to-mesenchymal transition (EMT) and is closely related to ferroptosis sensitivity in cancer cells, which can influence tumorigenesis from the early steps of cancer." (PMID 36555319, 2022). "As a key transcription factor of EMT, ZEB1 can induce EMT and metastasis in a variety of cancer cells." (PMID 35342341, 2022). "lncRNA XIST (human chromosome Xq13.2) overexpression in PDAC promotes cancer cell migration, invasion, and EMT via a typical ceRNA mechanism involving the sponging of miR-429 to modulate ZEB1 expression." (PMID 36452037, 2022). "ZEB1 and YAP represent two important routes for cancer development towards metastasis which are hyperactivated in different type of tumors, including OC." (PMID 35477522, 2022). "The upregulation of MMPs (MMP2, MMP9, and MMP13) was also reported in cancers overexpressing IL-32 along with other EMT markers including vimentin, Slug, Snail, and ZEB1, as well as they are well known for their contribution to cancer metastatic." (PMID 35281008, 2022). "In vivo and in vitro studies revealed the role of nesfatin-1 in cancer progression, particularly in the process of the development and invasion in RCC by increased EMT through the AMPK/TORC1/ZEB1 signalling pathway." (PMID 36553076, 2022). "Further experiments showed that knockdown of Zeb1 suppressed cell EMT and the invasive ability of embryonic cancer cell lines." (PMID 35611144, 2022). "When EHF-SF was overexpressed in MDA-MB-231 cells, the cell morphology was altered from spindle-like to cobblestone-like shapes, a change that was accompanied by repression of ZEB1 and ETS1 as well as in vitro cell migration and anti-cancer drug resistance." (PMID 33712555, 2021). "The downregulated projected network had 62 known regulatory interactions, of which transcription factors TAL1, ZEB1 and MEIS1 regulate the genes which were differentially regulated in more than half of the cancers studied." (PMID 34728699, 2021). "ZEB1 is a downstream target gene of TGFβ and has been reported to be a master regulator of the EMT and cancer metastasis." (PMID 34706749, 2021). "For example, ZEB1 controls inflammatory factor IL6, IL8 and IL1β production, which can induce cancer metastasis." (PMID 34916487, 2021). "However, in SCC, another necessary step in TGFβ-Notch1 induction of EMT is ZEB1-dependent inhibition of Notch3, suggesting that Notch1 and Notch3 may have different cancer-dependent roles in EMT induction and highlighting that the use of pan-Notch inhibitors may not be universally useful." (PMID 34680255, 2021). "Only EHF-SF abrogates ETS1-mediated activation of the ZEB1 promoter by promoting degradation of ETS1 proteins, thereby inhibiting the EMT phenotypes of cancer cells." (PMID 33712555, 2021). "The miR-200-ZEB1-E-cadherin axis has been clarified as a crucial pathway downstream of TGF-β in EMT while reciprocal repression between ZEB1 and the miR-200 family has recently been reported to promote EMT and invasion in cancer cells." (PMID 34638432, 2021).
cancer (continued). "It is well-known that the miR-200 family suppresses the EMT by inhibiting E-cadherin transcriptional repressors ZEB1 and ZEB2 in various types of cancers." (PMID 34208375, 2021). "Three proteins (PLAU, ZEB1, and MITF) were involved in the “transcriptional misregulation in cancer”." (PMID 34408977, 2021). "They affect the cancer’s aggressiveness and myofibroblast transdifferentiation via directly binding to EMT inducers ZEB1 and ZEB2." (PMID 34208375, 2021). "To further determine if B3GATL5 regulates EMT, we examined the expression of zinc finger E-box binding homeobox transcription factor 1 (ZEB1), which is the key factor to activate EMT and promote metastasis in cancers." (PMID 33413566, 2021). "Four proteins (PLAU, ITGA5, ZEB1, and ERBB3) were involved in “microRNAs in cancer” signaling pathway." (PMID 34408977, 2021). "Previous study indicated that EMT-inducing transcription factors (EMT-TFs) zinc finger E-box-binding homeobox 1 (ZEB1), which was highly expressed in invasive cells at the front of carcinomas, are critical inducer of EMT in cancer cells." (PMID 34969774, 2021). "This also applies to supporting the activities of zinc finger-containing transcription factors, some of which, such as ZEB1 and ZNF703, have been found to be human oncogenes responsible for pro-invasive and poorly differentiated stem-like cancer phenotype." (PMID 34572758, 2021). "ZEB1, considered as the target gene of miR-200 family, can repress E-cadherin to promote EMT process, subsequently bring about cancer progression." (PMID 33937049, 2021). "The EMT in cancer is a process of dedifferentiation due to external stimulation like TGF-β or IL-8, activation of transcription factors including Snail, Slug Twist, Zeb1, and Zeb2, or oncogenic signals like WNT, Notch, and MAPK pathways." (PMID 34622157, 2021). "Interactions between the miR-200 family of miRNAs and ZEB1/ZEB2, two transcription factors that regulate epithelial to mesenchymal transition (EMT), inhibited EMT and suppressed cancer metastasis)." (PMID 34055490, 2021). "In an in vitro study on bladder cancer, SFN induced the expression of miR-200c which, in turn, targeted ZEB1, leading to increased E-cadherin expression, suggesting that SFN acts as a TME modulator in this type of cancer." (PMID 34295245, 2021). "In recent years, growing evidences have indicated that ZEB1 (also known as TCF8, AREB6, ZFHEP, ZFHX1α, BZP, NIL-2α, deltaEF1) plays vital roles in EMT and cancer metastasis and its higher expression correlates with poor clinical outcomes in HCC patients 16-18." (PMID 33897890, 2021). "In particular, members of the miR-200 family inhibit EMT and cancer cell motility by suppressing Wnt/β-catenin signaling and directly interfering with the expression of EMT-TFs and in particular of ZEB1/2." (PMID 34036938, 2021). "ZEB1, HES1, NR6A1, PATZ1, PAX4 and MTF1—have a reported oncogenic role in cancer types other than HCC." (PMID 33541355, 2021). "Transcription factors known to regulate EMT include ZEB1, ZEB2, SNAI1 (SNAIL), SNAI2 (SLUG), and TWIST1 and have been suggested to promote cancer progression, including metastasis." (PMID 34339740, 2021). "Another important glucose transporter participating in EMT and cancer progression is GLUT-3, whose expression is upregulated by Zeb1, TCF4/β-catenin, HMGA1, and EGFR." (PMID 33673109, 2021). "TCGA database shows that LINC01296 level was significantly positively correlated with ZEB1 and ZEB2 levels in different cancers." (PMID 33854632, 2021). "In Neuroblastoma, circDGKB can sponge miR-873-5p to increase the expression of ZEB1 and GLI1, and promote the occurrence and development of cancer." (PMID 34676171, 2021). "For cancer metastasis, it is well known that the PI3K/Akt pathway regulates EMT master regulators such as ZEB1/2, Snail, Slug and Twist." (PMID 34549269, 2021).
cancer (continued). "Homeobox gene ZEB1 regulates the epithelial-mesenchymal transition (EMT) in cancer and embryonic development; miR-200 family plays a role in EMT by regulating the ZEB1 expression in the developing palate in mice." (PMID 34178974, 2021). "Similar to ZEB1, Snail has also been shown to play a major role in 5-FU-induced EMT in low- to advanced-grade malignant cancer cells." (PMID 34208465, 2021). "Zeb1 is a specific inducer of EMT, which ensures the manifestation of such properties as radioresistance and drug resistance by cancer stem cells." (PMID 34074001, 2021). "In cancer cells, E-cadherin is suppressed through the transcriptional repressors (SNAIL, SLUG, and ZEB1) binding to the E-cadherin promoter." (PMID 34917147, 2021). "Zinc‐finger E‐box‐binding homeobox 1 (ZEB1) is an important regulator of epithelial‐mesenchymal transition (EMT) and is involved in the maintenance of cancer stem cells (CSCs) via miR‐200c and BMI1 pathway." (PMID 33764690, 2021). "For restoring sensitivity to cancer therapies, the appropriate approaches regulating EMT-TFs, including Snail, Twist1, and ZEB1, are required." (PMID 33768509, 2021). "ZEB1 is master transcription factor that positively regulate invasion and metastasis by promoting EMT in cancer cells." (PMID 34234851, 2021). "In human malignant tumors, among the transcription factors involved in EMT, Snail plays a major inducing role, while Twist and Zeb1/2 are mainly involved in retaining the aggressive mesenchymal phenotype." (PMID 34193130, 2021). "We propose that the mechanisms involving MGAT5 in EMT processes is mediated by fine sensing of the stiffness leading to ZEB1 expression modulation, and regulate key oncogenic functions, making MGAT5 as a serious target to treat cancer." (PMID 33894774, 2021). "ZEB1 helps epigenetic silencing of CDH1 by bringing several enzymes to the E-cadherin promoter for epigenetic induction or by inhibiting the expression of stemness-repressing miRNAs to cause a dynamic transition of non-cancerous stem cells into cancer stem cells (CSCs) and vice versa." (PMID 34201896, 2021). "EMT-TFs belonging to the ZEB (ZEB1 and ZEB2), SNAIL (SNAIL1 and SNAIL2/SLUG), and TWIST (TWIST1 and TWIST2) families are best-studied in the context of cancer." (PMID 34638349, 2021). "ZEB1 drives EMT and confers chemotherapeutic resistance of cancer cells via directly altering the expression of a plethora of genes, like ESRP1 and ATM25,26." (PMID 33542225, 2021). "Studies have shown that binding to ZEB1 and a dependence on ZEB1 to inhibit E-cadherin expression is a mechanism by which oncogenes promote EMT and metastasis in cancer." (PMID 34210327, 2021). "As we have mentioned, miR-655 is an EMT-inhibiting miRNA targeting ZEB1 and TGFBR2 at the same time in cancers." (PMID 33902589, 2021). "Tks5 co-express with ZEB1, which is one of epithelial to mesenchymal transition (EMT) inducers, and Tks5 represent a mediator of invasive behavior of cancer cells." (PMID 34255789, 2021). "PDGF signaling has been related to increased EMT markers such as TWIST, SNAIL, ZEB1 and ZEB2 through several pathways in cancer cell-MSC interactions." (PMID 32726910, 2020). "Similar to TGF-β, ZEB1 is able to stimulate EMT in promoting invasion and metastasis of cancer cells." (PMID 32784711, 2020). "Expression of cancer stemness markers (PROM1 and LGR5), EMT genes (SNAI1, ZEB1 gene and CDH1) and percentage of ALDH + cells were evaluated to assess the effect of sinensetin in modulating cancer stemness and self-renewal." (PMID 33628166, 2020).